IFNAR2 (interferon alpha and beta receptor subunit 2)
Diseases named in the same sentence as IFNAR2 in open-access papers (continued):
Sharing a sentence is not in itself a finding about the gene and the disease.
COVID-19 (continued). "Interestingly, research suggests an inverse correlation between soluble IFNAR2 protein (sIFNAR2) levels and COVID-19 outcomes, with lower levels observed in deceased patients and higher levels in survivors." (PMID 39296547, 2024). "This study investigated the potential influence of SNPs in genes associated with the interferon pathway (IFNAR2 rs2236757), antiviral response (OAS1 rs10774671, OAS3 rs10735079), and viral entry (ACE2 rs2074192) on COVID-19 severity and their association with MAFLD." (PMID 39296547, 2024). "In conclusion, our data add to the accumulating evidence on the crucial role of interferon type I signaling and ISGs expression in severe COVID-19 cases, despite a lack of association between the phenotypes and the common polymorphism in the IFNAR2 gene." (PMID 39435115, 2024). "Future research focusing on post-transcriptional modifications in IFNAR signaling could fill current gaps and also hints at research on IFNAR2 expression among COVID-19 patients." (PMID 38741892, 2024). "Patients who express IFNAR2 poorly are more likely to be hospitalized for COVID-19." (PMID 38003785, 2023). "Additionally, IFNAR2 has a causal role based on Mendelian randomization result; increased expression of the interferon receptor subunit IFNAR2 reduced the odds of severe COVID-19 (P = 0.0043)." (PMID 37745867, 2023). "While we found symptoms of COVID-19 to influence genomic colocalization for select transcripts and states, as shown by IFNAR2 between severe and hospitalized COVID-19, this trend could have been influenced by a batch effect." (PMID 37640912, 2023). "Therefore, we decided to analyze another SNP, rs2236757 in IFNAR2 that has been found to contribute to disease severity of COVID-19." (PMID 36927455, 2023). "Variants of IRF1, IFNAR2 and DR1 associated with lower COVID-19 severity increase type I IFN signalling in lymphoid cells by upregulating IRF1 and IFNAR2 or downregulating DR1, attesting to the importance of efficient IFN signalling for a favourable clinical outcome." (PMID 37558883, 2023). "Smaller effects (odds ratios ~1.5 to 2.1) are attributed to common variants identified by COVID-19 GWAS studies, linked to genes involved in IFN signaling: risk SNPs in TYK2 and IFNAR2 genes, protective polymorphisms in the OAS1, OAS2, OAS3 cluster of genes, which are ISGs." (PMID 37334371, 2023). "Although the plasma levels of sIFNAR2 have not been previously reported, a reduced expression of IFNAR2 was associated with COVID-19 severity." (PMID 35967349, 2022). "Furthermore, we found reduced frequencies of type I interferon-producing plasmacytoid DCs and altered IFNAR2 expression on several myeloid cells in individuals recovered from severe COVID-19." (PMID 35291290, 2022). "Higher levels of sIFNAR2 were observed in survivors of COVID-19 compared to the group of non-survivors, which was not related to the studied IFNAR2 genetic variants." (PMID 35967349, 2022). "Our findings highlight the relevance of the IFNAR2 pathway in the severe COVID-19, so this could be considered for the clinical management of the diseases or the therapeutic design." (PMID 35967349, 2022). "Monocytes and dendritic cells, except cDC1s and pDCs, showed elevated expression of IFNAR2 in individuals recovered from severe and critical COVID-19 compared to unexposed healthy controls and mild and moderate COVID-19 group (Bonferroni-adjusted P-value range 0.04–4.95 × 10−5)." (PMID 36433939, 2022). "Using WES data, we focused on nine genes that have been reported to be involved in the SARS-CoV-2 entry pathway (ACE2, RAB7B, ADAM17, TMPRSS2), host immune response (IFNAR2, TYK2), and/or were previously shown to be associated with COVID-19 outcomes (DPP9, LZTFL1, SLC6A20)." (PMID 36292769, 2022). "Therefore, the relevance of the interferon pathway, mainly IFNAR2, in the COVID-19 severity has been evidenced at the genetic and transcription level and now with the amount of the soluble protein in plasma samples." (PMID 35967349, 2022).
COVID-19 (continued). "Furthermore, we find reduced frequencies of type I interferon-producing plasmacytoid DCs and altered IFNAR2 expression on several myeloid cells in individuals recovered from severe COVID-19." (PMID 36433939, 2022). "IFNAR2 is involved in innate antiviral defense, which is known to be important early in COVID-19." (PMID 34411000, 2021). "In particular, in COVID-19, a protective role of IFNAR2 has been suggested." (PMID 34557504, 2021). "Genetically predicted expression of IFNAR2 was associated with migraine in BioVU patients without severe COVID-19." (PMID 34315903, 2021). "We therefore tested whether the association of IFNAR2 p.F8S with severe COVID-19 was independent of top hit variants reported in previous GWAS (i.e., rs13050728, rs9636867 and rs2236757)." (PMID 41596638, 2026). "Further bioinformatic analyses have highlighted the potential role of rare variants in interferon receptor genes IFNAR1 p.Val168Leu, is associated with a reduced risk of severe COVID-19, while rare pathogenic variants in both IFNAR1 and IFNAR2 may impair antiviral signaling." (PMID 40410684, 2025). "Therefore, the objective of our study is to investigate genetic variants in the genes AQP3, ARHGAP27, ELF5, IFNAR2, LIMD1, OAS1 and UPK1A, which were selected due to the association of these genes with the severity of COVID-19, in a sample of Amazonian indigenous peoples." (PMID 38543725, 2024). "Another risk variant associated with increased IFNAR2 expression in classical monocytes was rs13050728 (allele T); in the Japanese population, the risk allele might contribute to severe COVID-19; these patients showed a low fraction of non-classical monocytes." (PMID 38003785, 2023). "It has been found that about 3.5% of COVID-19 patients had known autosomal-recessive (AR) deficiencies [interferon regulatory factor 7 (IRF7) and IFNAR1] and autosomal-dominant deficiencies (AD) [toll-like receptor 3 (TLR3), UNC93B1, TICAM1, TBK1, IRF3, IRF7, IFNAR1, and IFNAR2]." (PMID 34335535, 2021). "IL-10RB and IFNAR2 are encoded by adjacent genes and some cis-eQTLs for IL10RB are also cis-eQTLs for IFNAR2, making it difficult to determine which gene may be responsible for the association with COVID-19 and requiring further investigation." (PMID 33837377, 2021). "Beyond this example, colocalization analyses further validated the involvement of IFNAR2 and OAS1–3 genes in COVID-19 physiopathology." (PMID 40208878, 2025). "Previously, we have published and demonstrated the specific roles of the ACE2 rs2074192, IFNAR2 rs2236757, OAS1 rs10774671, CD40 rs4813003, and CASP3 rs113420705 genes in predicting severe COVID-19 and multisystem inflammatory syndrome (MIS-C) in children." (PMID 40066463, 2025). "This study highlights the significant impact of genetic variations in IFNAR2, OAS1, OAS3, and ACE2 on the clinical and laboratory outcomes of COVID-19 patients receiving Paxlovid treatment." (PMID 40278335, 2025). "We were unable to comment definitively on the prognostic power of IFNAR2 and TYK2 expressions in COVID-19 patients, and larger-scale studies are needed." (PMID 38741892, 2024). "Seven new genes (AQP3, ARHGAP27, ELF5, IFNAR2, LIMD1, OAS1 and UPK1A) were related to the severity of COVID-19 in populations of European origin." (PMID 38543725, 2024). "Despite discrepancies in findings regarding the downregulation of IFNAR2 and TYK2 in COVID-19 patients, the importance of these genes in the pathogenesis of COVID-19 remains prominent." (PMID 38741892, 2024). "Our findings also demonstrate a significant reduction in the expression levels of IFNAR2 and TYK2 among COVID-19 patients." (PMID 38741892, 2024). "Our study revealed that IFNAR2 and TYK2 mRNA expressions were significantly downregulated in COVID-19 patients compared to healthy subjects." (PMID 39351231, 2024).
COVID-19 (continued). "Another study developed in 34 Spanish hospitals with 11,939 positive cases of COVID-19 identified the relationship of the AQP3, ARHGAP27, ELF5, IFNAR2, LIMD1, OAS1 and UPK1A genes with the severity of the disease." (PMID 38543725, 2024). "Nevertheless, the potential of IFNAR2 and TYK2 expressions as prognostic biomarkers for COVID-19 has yet to be fully established." (PMID 38741892, 2024). "Allele T ACE2 rs2074192 (OR = 3.45; p = 0.009), allele A IFNAR2 rs2236757 (OR = 2.62; p = 0.039), allele A OAS1 rs10774671 (OR = 4.60; p = 0.003) and allele C CD40 rs4813003 (OR = 4.75; p = 0.037) are associated with severe COVID-19 that could advance to MIS-C." (PMID 37896870, 2023). "Crucial factors for the development of severe COVID-19 or MIS-C are sex (male gender), ACE2 rs2074192, IFNAR2 rs2236757, OAS1 rs10774671, CD40 rs4813003 and CASP3 rs113420705." (PMID 37896870, 2023). "Additional case reports of a few of these autosomal IEIs in patients with life-threatening COVID-19 have been documented implicating IFNAR1, IFNAR2, and TBK1." (PMID 35768520, 2022). "Known significant loci for COVID-19 severity in 3p21.31 (near SLC6A20 and LZTFL1) and 21q22.11 (in IFNAR2) were clearly replicated at genome-wide significance in this study, specifically for risk of infection, hospitalization and severity." (PMID 35708486, 2022). "We found that in the BD–COVID-19 interaction, genes RRM2, IFNAR2, and SLC7A11 and miRNAs hsa-mir-30a-5p, hsa-mir-93-5p, and hsa-mir-192-5p have more significant effects." (PMID 35185890, 2022). "The expression of genes IFNAR2 and TYK2 was found to be related to critical illness and severity of COVID-19 symptoms." (PMID 34411000, 2021). "Despite these limitations, this study has some consistency with a recent MR study searching systematically for COVID-19 druggable targets that homed in on drugs targeting ACE2 and IFNAR2 or IL10RB." (PMID 34911594, 2021). "IFN genes IFNG and IFNE, and IFN receptors IFNAR2 and IFNGR2, were upregulated in COVID-19 vs non-COVID19, suggesting a crucial role for IFN-signaling in mounting an anti-SARS-Cov-2 response." (PMID 33473155, 2021). "Several other loci show no previously documented genome-wide significant associations, despite the high significance and attractive candidate genes for COVID-19 (for example, CXCR6, LZTFL1, IFNAR2 and OAS1/OAS2/OAS3 loci)." (PMID 34237774, 2021). "Other Neanderthal-related haplotypes reported to correlate with the severity of COVID-19 include genetic elements coding for the DPP9 protein (chr19, p13.3 –lead SNP: rs2109069) and the interferon alpha receptor (IFNAR2) protein (coding chr21, q22.1 –lead SNP: rs2236757)." (PMID 39752416, 2025). "Although our findings did not reveal a substantial impact of the IFNAR2 rs2236757 genotype on COVID-19 severity or clinical outcomes, an interesting observation emerged." (PMID 39296547, 2024). "Hence, additional research on IFNAR2 and TYK2 expression in COVID-19 can significantly contribute to finding a conclusive treatment for this worldwide crisis." (PMID 39351231, 2024). "Additionally, IFNAR2 and TYK2 were significantly downregulated in the COVID-19 group compared to healthy subjects (p-value = 0.002 and p-value = 0.028, respectively)." (PMID 38741892, 2024). "In other words, IFNAR2 and OAS are both key genes in the coronavirus disease-COVID-19." (PMID 36525367, 2023). "In conclusion, this study shows an association of rs1799752/ACE1, rs1990760/IFIH1, rs2236757/IFNAR2, rs12329760/TMPRSS2, and rs2304256/TYK2 polymorphisms with worse COVID-19 outcomes, especially among female and non-white patients." (PMID 36672770, 2022). "On the contrary, we observed increased expression of IFNAR2 on basophils and myeloid cells but not on B cells and pDCs in individuals recovered from severe COVID-19." (PMID 36433939, 2022).
COVID-19 (continued). "Overall, in addition to predisposing individuals to COVID-19-related hospitalization and outcome severity, increased IL10RB and decreased IFNAR2 GReX are associated with respiratory failure independent of COVID-19 exposure." (PMID 36064543, 2022). "Finally, we found IFNAR1 and IFNAR2, a receptor for type I interferon (IFNα) to be upregulated in the CD4+ TCM and classical monocytes of the COVID-19 patients, compared to the others." (PMID 36532041, 2022). "Our findings prioritize trials of drugs targeting IFNAR2 and ACE2 for early management of COVID-19." (PMID 33837377, 2021). "Genetic variations within IFNAR2, OAS1, and OAS3 could potentially disrupt this signaling pathway, leading to decreased protein abundance, impaired receptor internalization, or altered ligand interactions, thereby exacerbating the severity of COVID-19." (PMID 40278335, 2025). "In addition, IFNAR2 differed across four tissues (intestine, lung, brain, and blood) in five bulk RNA-seq data sets (GSE149312, GSE152586, GSE164332, GSE171110, and GSE179850), revealing more subtle differences in the molecular mechanisms of COVID-19." (PMID 39714149, 2025). "Moreover, the cohort analysis of 694 Brazilian COVID-19 patients reveals a significant link between rs2236757/IFNAR2 and rs2304256/TYK2 polymorphisms and worsened COVID-19 outcomes, particularly affecting female and non-white patients." (PMID 39351231, 2024). "After adjusting for potential confounding factors (age, sex, and history of COVID-19 vaccination injection), we observed a negative correlation between the expression levels of IFNAR2 and TYK2 transcripts in COVID-19 patients (p-value = 0.044; partial correlation coefficient = -0.283)." (PMID 38741892, 2024). "However, neither IFNAR2 nor TYK2 expression was significantly different between the case subgroups based on COVID-19 severity." (PMID 38741892, 2024). "The two variants with eQTL effects in monocytes of the COVID-19 patients had significant eQTL effects specifically in cMono (FDR = 2.6 × 10−6 for ABO and FDR = 0.017 for IFNAR2), and no such eQTL effect of the IFNAR2 variant was observed in the healthy controls (FDR = 0.66)." (PMID 37095364, 2023). "The frequency of ACE2 rs2074192, IFNAR2 rs2236757, OAS3 rs10735079, FCGR2A rs1801274 and CASP3 rs113420705 genotypes did not follow the Hardy–Weinberg equilibrium (p < 0.05) due to the directional selection made in our study (focusing on patients with COVID-19)." (PMID 37896870, 2023). "This suggests that the increased IFNAR2 (but not IL10RB) levels observed in the most severe group of COVID-19 patients may reflect the increased likelihood of SARS-CoV-2 viremia in those patients." (PMID 36064543, 2022). "We could not recruit individuals with mild or moderate COVID-19 since the study center is a tertiary-care hospital; therefore, the relevance of IFNAR2 in less severe COVID-19 or asymptomatic individuals requires further investigation." (PMID 35967349, 2022). "Finally, we neither observed any influence of the IFNAR2 rs2236757, rs1051393, rs3153, rs2834158, and rs2229207 on the sIFNAR2 plasma levels in individuals with severe COVID-19." (PMID 35967349, 2022). "Specifically, we observed a negative correlation between the expression levels of IFNAR2 and TYK2 transcripts in COVID-19 patients." (PMID 39351231, 2024). "Based on our findings, the negative correlation between IFNAR2 and TYK2 expression levels, even after adjusting for confounding factors, highlights their potential role in COVID-19 pathogenesis." (PMID 38741892, 2024). "There was a negative correlation between the expression levels of IFNAR2 and TYK2 transcripts in COVID-19 patients (p-value = 0.044; partial correlation coefficient = -0.283)." (PMID 38741892, 2024). "Our study did not establish that the expressions of IFNAR2 and TYK2 genes serve as a predictor of severity of COVID-19, likely due to limitations such as small sample size." (PMID 39351231, 2024).
viral infection (48 papers, 2008 to 2026). "LOF variants of IFNAR1 and IFNAR2 are common in Western Polynesia and the Arctic, where they underlie viral disease in homozygotes." (PMID 39680367, 2025). "Surprisingly, only a few viral diseases have been reported in patients with IFNAR1 or IFNAR2 deficiency." (PMID 36719370, 2023). "The penetrance of severe LAV and WT viral disease appears to be incomplete in patients with IFNAR1 or IFNAR2 deficiency." (PMID 35442418, 2022). "However, other genetic variants of IFNAR2 with interesting associations in viral disease have been reported." (PMID 38003785, 2023). "Individuals with autosomal recessive IFNAR1 deficiency described thus far, including our patient, were aged 6 months to 38 years and, surprisingly, had suffered from relatively few viral infections, consistent with the clinical features of patients with IFNAR2 deficiency." (PMID 35091979, 2022). "The IL10RB and IFNAR2 share an inverse relationship for viral infection, wherein macrophages have been reported to secrete higher IL10 in comparison to IFNAR246." (PMID 34315903, 2021). "These and our previously published results imply that the presence of IFNAR2 is sufficient for controlling viral infection in Ifnar1−/− mice, but the presence of IFNAR1 in Ifnar2−/− mice is not." (PMID 30473701, 2018). "In our study, we unequivocally demonstrated that, at least for P. alecto IFN-α3, IFN-α pathway is fully dependent on IFNAR2 by transcriptomics-based analysis, suggesting that IFNAR2 is indispensable for defending against virus infection in bats." (PMID 28793350, 2017). "Autosomal recessive deficiency of the IFNAR1 or IFNAR2 chain of the human type I IFN receptor abolishes cellular responses to IFN-α, -β, and -ω, underlies severe viral diseases, and is globally very rare, except for IFNAR1 and IFNAR2 deficiency in Western Polynesia and the Arctic, respectively." (PMID 39680367, 2025). "IFNα/β exerts antiviral activity by binding to the IFNAR1/IFNAR2 complex during viral infection." (PMID 40001503, 2025). "The penetrance of severe LAV and naturally acquired viral diseases seems to be incomplete, as previously seen in patients with AR complete IFNAR1 or IFNAR2 deficiency, whereas penetrance is higher for infections with certain viruses, such as SARS-CoV-2 than for HSV-1." (PMID 39680367, 2025). "The viral infection still could be inhibited even the co-treatment was added after HSV-1-GFP virus infection or anti-IFNAR2 antibody pretreatment." (PMID 38408104, 2024). "IFNAR2 encodes subunit 2 of the interferon-α/β receptor (IFNAR), mediating the roles of type 1 interferons α and β in innate immune response to viral infections." (PMID 36051697, 2022). "Additionally, we found that P-STAT3 inhibition did not alter susceptibility of Ifnar2−/− mice to BSI on day 3, indicating that IFNAR1 and IFNAR2 induce disparate mechanisms in response to viral infection." (PMID 30473701, 2018). "This situation can readily be observed in deficiencies of STAT2, TYK2, IFNAR1, and IFNAR2, in which severe viral disease affects some but not all individuals, with a greater penetrance observed for infections with live-attenuated viral vaccines than for common viral infections of childhood." (PMID 41608500, 2025). "While increased expression of the genes for alpha/beta or type I interferon type I (IFN-I) receptors, IFNAR1 and IFNAR2, and enhanced signaling of type I interferon pathways might be assumed to serve as protective factors due to their crucial role in controlling viral infections." (PMID 39457216, 2024). "That IFNAR2 deficiency resulted in increased neutrophil recruitment and an increased level of LDH production by day 7 of IAV infection further suggests that IFNAR2 may also control damage response during viral infections." (PMID 30473701, 2018). "Missense mutations were identified in the IFN-α receptors 1 and 2 (IFNAR1 and IFNAR2), the IFNGR2, the IFNLR1, receptors critical for the response to viral infections." (PMID 41522351, 2026).